CSTB (cystatin B)
Diseases named in the same sentence as CSTB in open-access papers (continued):
Sharing a sentence is not in itself a finding about the gene and the disease.
autosomal recessive disease (2 papers, 2019 to 2022). Autosomal recessive form of disease. "Unverricht-Lundborg disease (ULD), also called EPM1 is the most common type of PME; It is an autosomal recessive disease caused by the mutation of the cystatin B gene (CSTB)." (PMID 35478698, 2022). "EPM1A is an autosomal recessive disease, and the genotype of the patients most commonly attain an unstable dodecamer expansion repeat in the promoter region of the CSTB gene, which decreases the gene transcription." (PMID 31467503, 2019).
benign tumor (2 papers, 2013 to 2014). "There was no significant change in serum cystatin B in the benign tumour group versus control serum." (PMID 23986888, 2013).
genetic disease (2 papers, 2022 to 2024). "ULD is a genetic disease mainly caused by an abnormal expansion of a dodecamer sequence located on the CSTB gene promoter." (PMID 36359887, 2022).
kidney disease (2 papers, 2021 to 2025). "Potentially, urine cystatin B and clusterin may be used to diagnose active kidney disease allowing for more appropriate therapeutic interventions and ultimately better supportive care." (PMID 34324590, 2021).
neurological disease (2 papers, 2016 to 2024). "Thirdly, we present 19 protein control concentration values, four of which (sortilin, CCL16, cystatin B, KLK5) have not, to our knowledge, previously been reported for adult individuals without neurological disease." (PMID 26914813, 2016).
bacterial disease (1 paper, 2025). "In the present study, the CSTB was cloned and characterized from Nile tilapia (On-CSTB) and its role in bacterial infection was revealed." (PMID 41017465, 2025). "The function of On-CSTB on inflammatory factors expression during bacterial infection was further detected via qPCR." (PMID 41017465, 2025). "In conclusion, we identified and characterized cystatin B (On-CSTB) from Nile tilapia and explored its role in the immune response to bacterial infection." (PMID 41017465, 2025). "Therefore, this study aimed to characterize the function of Nile tilapia CSTB in inflammatory regulation and determine its involvement in key immune signaling pathways during bacterial infection." (PMID 41017465, 2025).
brain diseases (1 paper, 2022). "The physiological function of CSTB is largely unknown, and the mechanisms underlying the human brain diseases remain poorly understood." (PMID 36533126, 2022).
neurodevelopmental disorder (1 paper, 2022). A behavioral and cognitive disorder with onset during the developmental period that involves impaired or aberrant development of intellectual, motor, or social functions. "Cystatin B (CSTB) serum level was strongly associated with autistic features in a recent twin study on ASD and other neurodevelopmental disorders." (PMID 36339838, 2022).
CSTB also shares sentences with these, for which no sentence is quoted: Progressive myoclonic epilepsy (6 papers); Cognitive impairment (3); schizophrenia (3); benign ovarian tumours (2); ceroid lipofuscinoses (2); cognitive decline (2); juvenile myoclonic epilepsy (2); Lafora disease (2); sialidosis (2); amyloid disease (1); Anxiety (1); apraxia (1); arachnodactyly (1); Arthritis (1); autism spectrum disorder (1); axonal neuropathy (1); Brain atrophy (1); brain cancer (1); cerebellar ataxia (1); Cerebellar atrophy (1); Cerebral ischemia (1); chronic kidney disease (1); congenital heart disease (1); cortical atrophy (1); cortical dysplasia (1); dentatorubral-pallidoluysian atrophy (1); Dyskinesia (1); emotional instability (1); endometrial adenocarcinoma (1); endometrial cancer (1).
A further 30 diseases each share a sentence with CSTB in 1 paper.